SNORD88A (small nucleolar RNA, C/D box 88A)
Synonyms: HBII-180A
Gene: Small nucleolar RNA gene on chromosome 19 (50,799,442 to 50,799,532, reverse strand). Ensembl gene ENSG00000221241.
Gene Ontology:
Biological process: RNA processing
Cellular component: nucleolus
Homologues: Orthologues: chimpanzee SNORD88A (100% identical), macaque SNORD88A (93% identical), dog SNORD88A (89% identical), mouse Snord88a (86% identical), mouse Snord88c (86% identical), mouse Gm23991 (74% identical), mouse Gm54694 (46% identical). Paralogues in human: SNORD88B (91% identical), SNORD88C (88% identical).